BRCA2 (BRCA2 DNA repair associated)
Diseases named in the same sentence as BRCA2 in open-access papers (continued):
Sharing a sentence is not in itself a finding about the gene and the disease.
ovarian carcinoma (continued). "The risks of breast and ovarian cancers in female relatives of BRCA1 and BRCA2 carriers were significantly higher than female relatives of non-carriers (BRCA1: RR = 4.29, P < 0.001 and RR = 21.95, P < 0.001; BRCA2: RR = 4.19, P < 0.001 and RR = 4.65, P < 0.001, respectively)." (PMID 36861435, 2023). "Previous findings have suggested that the distribution of ovarian cancer histopathology subtypes differs in germline BRCA1 and BRCA2 pathogenic variant carriers, compared to non-carriers, with a similar distribution associated with pathogenic variants for the two genes." (PMID 37076566, 2023). "In addition to female breast and ovarian cancers, BRCA1 and BRCA2 PVs are associated with increased risks of male breast, pancreatic, stomach, and prostate (only BRCA2 PVs) cancers, but not with the risks of other previously suggested cancers." (PMID 35077220, 2022). "However, the relationship between both BRCA2 and MAGEC3 protein expression and their combined clinical significance in ovarian carcinoma is unknown." (PMID 36230652, 2022). "Onset of breast and ovarian cancer is similar between BRCA2 carries and non-BRCA families." (PMID 35469032, 2022). "Although germline BRCA1 and BRCA2 (BRCA1/2) pathogenic variants account for a large proportion of Hereditary Breast and Ovarian Cancer (HBOC), a Scottish study on BRCA1/2 testing in ovarian cancer revealed that 48% of pathogenic variants did not fulfil family history criteria for testing." (PMID 35190596, 2022). "An additional 3 breast and ovarian cancer cases were not analyzed in this cohort because in additional to RAD51B germline mutations, they carried another high or moderate penetrance mutation in a cancer susceptibility gene (1 each BRCA2, RAD51D, ATM)." (PMID 34635660, 2021). "Familial ovarian cancer (OC) cases not harbouring pathogenic variants in either of the BRCA1 and BRCA2 OC-predisposing genes, which function in homologous recombination (HR) of DNA, could involve pathogenic variants in other DNA repair pathway genes." (PMID 34861889, 2021). "Still, currently there is no clear rationale regarding which PARPi to use, for which ovarian cancer patients beyond FDA endorsement of olaparib, rucaparib or niraparib when a mutation is present in BRCA1 or BRCA2 after first-line platinum-based chemotherapy or as maintenance therapy." (PMID 34445211, 2021). "Our result suggested that the BRCA2 gene might not play a considerable role in pathogenesis of ovarian cancer in Vietnamese patients." (PMID 32856862, 2020). "Therefore, we undertook screening of other genes in a cohort of patients with a presumed genetic predisposition for breast and ovarian cancer, in whom germline mutations in BRCA1 and BRCA2 were previously ruled out." (PMID 32756499, 2020). "The purpose of our study was to address the issue of missing heritability in ovarian cancer by focusing on 48 women with a personal history of OVCA and who were at high risk of genetic inheritance but had no known pathogenic variant in BRCA1/BRCA2." (PMID 28591191, 2017). "In our previous study, we demonstrated that mutations of eight members of the ADAMTS family (including ADAMTS16 gene) were significantly associated with chemotherapy sensitivity and longer survival in patients with ovarian cancer, independent of BRCA1 or BRCA2 mutations." (PMID 29179445, 2017). "Genetic factors predisposing to breast and ovarian cancer primarily remain unknown in HBOC families negative for BRCA1 and BRCA2 mutations." (PMID 28738860, 2017). "BRCA2 does not present a similar methylation profile in ovarian cancer." (PMID 26800494, 2016). "Brazilian inhabitants may have peculiar genetic characteristics associated with ethnic diversity, and studies focusing on the entire BRCA1/BRCA2 gene sequencing in Brazilian ovarian cancer patients are still lacking." (PMID 27914478, 2016).
ovarian carcinoma (continued). "It is also well established that mutation carriers are significantly enriched in those women with ovarian cancer who also have a strong family history of breast and/or ovarian cancer, although a cancer family history is not a reliable method for identifying women with BRCA1/BRCA2 mutations." (PMID 25884701, 2015). "BRCA1 and BRCA2 exons were amplified using the Ion AmpliSeq BRCA1/2 Panel and sequenced on the Ion Torrent PGM sequencer in 512 women with familial and/or only early onset breast and/or ovarian cancers who were negative for selected BRCA1/2 mutations." (PMID 25948282, 2015). "A substantial percentage of BRCA1/2 positive patients diagnosed after the age of 60 (n = 8/20) is consistent with the previous reports, indicating that the incidence of ovarian cancer in older age does not exclude BRCA germline mutation, especially as far as the BRCA2 gene is concerned." (PMID 25366421, 2015). "BRCA2 does not exhibit a similar methylation profile in ovarian cancer." (PMID 24821107, 2014). "Thus, BRCA2 germline mutations are currently the most frequently identified genetic alteration in FPC even in the absence of breast and/or ovarian cancer." (PMID 24624093, 2014). "Of the remaining 64 women diagnosed at ages 36 through 50 years, but with no family history of breast or ovarian cancer, 47 women were screened for germline mutations in BRCA1 and BRCA2 genes, and three BRCA1 and one BRCA2 carriers were identified (mutation prevalence, 8.5%)." (PMID 23116406, 2012). "Excess of EMSY protein, that results from gene amplification, could contribute to the tumorigenesis of a substantial proportion of non-inherited sporadic breast and ovarian cancers, by silencing BRCA2." (PMID 21939546, 2011). "The DNA of 40 healthy Slovenian women aged between 50 and 69 years without any personal and familial breast and/or ovarian cancer history was also tested for the presence of all known mutations, UVs and polymorphisms in BRCA1 and BRCA2 genes in Slovenian population." (PMID 21232165, 2011). "Recently, RAD51C, essential for homologous recombination repair, has been reported to be a rare hereditary breast and ovarian cancer susceptibility gene and several pathogenic RAD51C mutations have been identified in BRCA1- and BRCA2-negative hereditary breast and ovarian cancer families (HBOC)." (PMID 21980511, 2011). "Therefore, a number of PARP-inhibiting analogues are currently undergoing clinical trials for BRCA1 and BRCA2 negative advanced breast and ovarian cancers as well as BRCA2 negative prostate cancer." (PMID 21261999, 2011). "In addition, literature data on the occurrence of BRCA1, BRCA2, CHEK2 and NBS1 mutations in non-selected ovarian cancer patients were reviewed." (PMID 19338682, 2009). "These families had previously tested negative for mutations in known ovarian cancer predisposition genes, including BRCA1 and BRCA2, and thus the underlying genetic predisposition in these families is currently unknown." (PMID 15918899, 2005). "There was some evidence for a nonbreast/ovarian cancer risk difference by age at first BC diagnosis in noncarriers (under 45 years: SIR, 1.68 [95% CI, 1.39 to 2.01]; 45 years or over: SIR, 1.15 [95% CI, 1.02 to 1.28]), which we did not observe for BRCA1/BRCA2 PV carriers." (PMID 39475295, 2025). "Of the predicted pathogenic (i.e., loss-of-function) BRCA1/2 variants in ovarian cancer that had been discarded (n = 2), one variant is characterized as ‘Pathogenic’ by a single submitter (BRCA1 S324fs*17; ClinVar Variation ID: 946287), while the other is absent from the database (BRCA2 I979fs*12)." (PMID 37568048, 2023). "We hypothesize that postponement of oophorectomy after salpingectomy, to the age of 40–45 (BRCA1) or 45–50 (BRCA2) years, compared with the current standard salpingo-oophorectomy at age 35–40 (BRCA1) or 40–45 (BRCA2) years, is non-inferior in regard to tubo-ovarian cancer risk." (PMID 37045546, 2023).
ovarian carcinoma (continued). "Notably, AZD compounds did not change the mRNA expression of BRCA1/BRCA2 in ovarian cancer cells; however, AZD8835 could downregulate BRCA1/BRCA2 mRNA in KRAS-mutated OVCAR-8 cell via ERK signaling." (PMID 32194423, 2020). "No cases of ovarian cancer had been found in the III generation female in this family, but genetic tests have shown that there were 1342A>C single mutations in the BRCA2 gene in III2, III4, and III7, and there were two mutations of BRCA1 (3326A>T) and BRCA2 (1342A>C) in III8." (PMID 32356124, 2020). "There is evidence that genetic testing soon after ovarian cancer diagnosis does not add to the negative psychological response caused by the cancer diagnosis itself, but that finding out about BRCA1/BRCA2 carrier status may lead to a slight increase in the psychological burden at that time." (PMID 28780755, 2017). "Cells lacking the major hereditary breast/ovarian cancer predisposition genes, BRCA1 or BRCA2, or certain other HR-defective cells, reveal a bias in favor of long tract gene conversion, suggesting that this aberrant HR outcome might be connected with genomic instability." (PMID 27832076, 2016). "For ovarian cancer, LOF mutations were not enriched in hGIS1 genes (P=0.87) but were enriched in hGIS2 genes (P<0.0001); this increase in significance was due to the presence BRCA1 and BRCA2 in the hGIS2 gene list, which accounted for 70% of the LOF mutations in hGIS2 genes." (PMID 27071721, 2016). "Women with a BRCA1 or BRCA2 mutation who have not chosen prophylactic salpingo-oophorectomy may follow determination of Ca125 and transvaginal ultrasound since age 35 (IIC), but they should be informed that early detection of ovarian cancer is not guaranteed." (PMID 26669313, 2015). "The majority of this benefit was in the BRCA1/BRCA2 wild-type (or unknown) group, perhaps demonstrating that combinations can overcome monotherapy dependencies but also highlighting that there is still a lot to learn about biomarkers for anti-angiogenic and PARP inhibitor agents in ovarian cancer." (PMID 26557500, 2015). "Furthermore, 45.8% of breast/ovarian cancer patients with inherited BRCA1 and BRCA2 mutations do not have a clear family history due to a small family structure, predominance of males in the family and/or paternal inheritance, adoption or non-biological father." (PMID 23536787, 2013). "Thus, it has been hypothesized that mutations of other functional partners in the BRCA pathway could account for a subset of breast and ovarian cancers lacking BRCA1 and BRCA2 mutations." (PMID 22792303, 2012). "Ten-year cumulative CBC, ovarian, and combined nonbreast/ovarian cancer risks were 16%/6.3%/7.8% (BRCA1 carriers), 12%/3.0%/6.2% (BRCA2 carriers), and 3.6%/0.4%/4.9% (noncarriers)." (PMID 39475295, 2025). "A 37-year-old premenopausal woman, with no family history of breast or ovarian cancer, and confirmed germline BRCA1 and BRCA2 wild-type, was referred to our institution following a left breast tumorectomy performed at another hospital." (PMID 41018107, 2025). "In ovarian cancer, BRCA1/BRCA2 HRD detection is concordant across 20 assays, but non-BRCA HRD varies (correlation 0.4–0.9), risking 20% missed cases." (PMID 40864792, 2025). "While their role in OSCC is not as well-defined as in breast and ovarian cancers, emerging evidence suggests that BRCA1 and BRCA2 contribute to tumor initiation, progression, and therapeutic resistance." (PMID 40224184, 2025). "Noncarriers had elevated CBC and nonbreast/ovarian cancer SIRs, which were lower than the corresponding BRCA1-or BRCA2-specific SIRs (CBC: SIR, 3.03 [95% CI, 2.67 to 3.43]; nonbreast/ovarian: SIR, 1.26 [95% CI, 1.14 to 1.38])." (PMID 39475295, 2025). "The most notable example so far is the use of PARP inhibitors (PARPi) to treat individuals with inherited breast and ovarian cancers lacking wild-type copies of the BRCA1 and BRCA2 genes." (PMID 39987121, 2025).
ovarian carcinoma (continued). "BRCA1/BRCA2 PV carriers had elevated combined nonbreast/ovarian cancer SIRs (BRCA1: SIR, 2.18 [95% CI, 1.59 to 2.92]; BRCA2: SIR, 1.68 [95% CI, 1.24 to 2.23])." (PMID 39475295, 2025). "As the PoC endpoint is neither breast nor ovarian cancer, these data do not suggest that our system is more informative than BRCA1 and BRCA2 for these malignancies specifically." (PMID 39226245, 2024). "CNVs analysis showed that 287 samples (including No. 7–12) were CNV-negative, while five patients with ovarian cancer (No. 1–5) and one patient (No. 6) with pancreatic cancer were identified to carry CNVs in BRCA1 or BRCA2 genes." (PMID 38274092, 2023). "A total of 281 samples were found to be CNV-negative, while 11 patients with ovarian cancer (No. 1–5, 7–12) and one patient with pancreatic cancer (No. 6) were identified to carry CNVs in BRCA1 or BRCA2 genes by MS assay." (PMID 38274092, 2023). "The assembled dataset consisted of 10,373 ovarian cancer cases, including 2044 germline BRCA1 carriers, 761 germline BRCA2 carriers and 7568 non-carriers (based on germline testing)." (PMID 37076566, 2023). "In high-grade ovarian cancer, tumors with alterations in BRCA1, but not BRCA2, for example, demonstrated a more immunoreactive phenotype characterized by higher levels of TILs." (PMID 36077694, 2022). "In our study’s for 56% (10/18) of all patients with BRCA1 origin ovarian cancer the PV was located in the OCCR published in the study of Rebbeck15, whereas for BRCA2 origin ovarian cancer no PV were located in the ovarian cluster region." (PMID 35469032, 2022). ",17, 18, 19 Use of response to induction platinum-based therapy has consistently been used as a surrogate to enrich for PARP-sensitive ovarian cancer subpopulations irrespective of BRCA1 and BRCA2 status." (PMID 35990583, 2022). "Among ovarian cancer patients, BRCA1 and especially BRCA2 carriers respond better than non-carriers to platinum-based chemotherapy and have prolonged survival." (PMID 35494038, 2022). "A family history of ovarian cancer was only seen in BRCA1/2 families but not in PALB2 families, where 28.3% of BRCA1 carriers and 12.3% of BRCA2 carriers had a family history of ovarian cancer (p-value = 0.001 and 0.018, respectively)." (PMID 34439348, 2021). "Several studies, including a large meta-analysis encompassing almost 8000 ovarian cancer cases, have reported that BRCA1 and BRCA2 carriers have better survival than non-carriers, but the survival advantage diminishes with time from diagnosis." (PMID 33670479, 2021). "The cumulative risks for both breast and ovarian cancer at OCCR were not higher than those at the other two BCCRs for both Korean BRCA1 and BRCA2 carriers." (PMID 34063308, 2021). "Several studies have shown that among ovarian cancer patients, BRCA1 and especially BRCA2 carriers respond better than non-carriers to platinum-based chemotherapy and have prolonged survival." (PMID 32341426, 2020). "AZD compounds did not change the mRNA expression of BRCA1/BRCA in ovarian cancer cells, but AZD8835 inhibited BRCA1/BRCA2 mRNA expression and p-ERK protein expression in OVCAR-8 cells with the KRAS mutation." (PMID 32194423, 2020). "New findings that RAD52 is essential for cell viability in BRCA1-, PALB2- and BRCA2- and RAD51 paralog-deficient cells, but not in normal cells, suggested that RAD52 may represent an attractive therapeutic target for killing hereditary breast cancer and ovarian cancer cells." (PMID 27649245, 2016). "A prevalence of 2.1% for BRCA1 large genomic rearrangements has been detected in Spanish hereditary breast/ovarian cancer families testing negative for point variations and small insertions/deletions in BRCA1 and BRCA2." (PMID 24906410, 2014). "Second, of women who had a family history of breast and/or ovarian cancer, 42.1% of women with TNBC were BRCA1 or BRCA2 carriers compared with 14.2% of those with non-TNBC (P = < 0.0001)." (PMID 23116406, 2012).
ovarian carcinoma (continued). "The consequences of defective homologous recombination (HR) are not understood in sporadic ovarian cancer, nor have the potential role of HR proteins other than BRCA1 and BRCA2 been clearly defined." (PMID 22253870, 2012). "The estimate of ovarian cancer was also very similar with risks to 70 years of 60% for BRCA1 carriers and 33% as opposed to 27% for BRCA2 carriers." (PMID 18513387, 2008). "Individual women with both breast and ovarian cancer were recorded in 36% of BRCA1 families, with up to three instances per family, whereas they occurred in only 10% of BRCA2 families and no family included more than one case." (PMID 12698193, 2003). "Additionally, when considering a family history of ovarian cancer, BRCA1 showed a high odds ratios of 8.96, whereas BRCA2 did not exhibit such a significance compared to BRCA1." (PMID 40323562, 2025). "The fact that we did not observe the induction of mCCL5 in our Brca2 knockout mouse experiments may be explained by epigenetic silencing described in the ID8 model and human HRD ovarian cancer cells." (PMID 40579444, 2025). "Furthermore, though CDK12 inactivation in the Skov3 ovarian cancer cells showed some preferential downregulation of long genes overall, BRCA1 and BRCA2 protein were not affected." (PMID 39071291, 2025). "Similarly, in September 2020, the Ministry approved niraparib as a maintenance treatment for patients with newly diagnosed, platinum-sensitive epithelial ovarian cancer, regardless of BRCA1 or BRCA2 status." (PMID 39590126, 2024). "We found that the risks for breast and ovarian cancers in the female relatives of BRCA1 and BRCA2 carriers were significantly higher than non-carriers, and the risks for pancreatic and prostate cancers in male relatives of BRCA2 carriers were also significantly increased." (PMID 36861435, 2023). "As a first step in resolving the missing heritability of ovarian carcinoma, we present WES data from a large cohort of women diagnosed with HGSOC, who were tested through a familial cancer clinic but returned negative findings for the BRCA1 and BRCA2 genes." (PMID 32242007, 2020). "Of the women with low familial risk of breast and ovarian cancer (diagnosed 36 to 50 with no family history of breast or ovarian cancer], 6.4% and 1.7% of women with TNBC and non-TNBC were found to be BRCA1 carriers, respectively, whereas 2.1% and 5.0% were BRCA2 carriers." (PMID 23116406, 2012). "The limitations are the underestimation of the frequency of carriers in families with ovarian cancer and in families with prostate cancer, the non-applicability to ethnic minorities, the impossibility of incorporating third-degree relatives, and non-inclusion of other genes besides BRCA1/BRCA2." (PMID 38672070, 2024). "In ovarian cancer OVCA433 cells, the interruption of Aur A did not alter the expression of Aur B, but the knockdown of Aur B enhanced the expression of Aur A. The silencing of Aur A or/and Aur B promoted the expressions of BRCA1 and BRCA2, compared with in scrambled shRNA-treated control cells." (PMID 24775809, 2014).